JAK2 (Janus kinase 2)
Diseases named in the same sentence as JAK2 in open-access papers (continued):
Sharing a sentence is not in itself a finding about the gene and the disease.
cardiovascular disease (20 papers, 2018 to 2026). "The p-values associated with the effect sizes of JAK2 V617F on circulatory system diseases were large." (PMID 39062663, 2024). "Several studies have demonstrated that phytochemicals and natural plants exert a protective effect against cardiovascular diseases and regulate JAK2/STAT3 signaling." (PMID 40647133, 2025). "The regulation of JAK2 phosphorylation and its downstream pathways has the potential to ameliorate inflammation, making JAK2 a prospective therapeutic target for preventing and managing cardiovascular diseases (CVDs)." (PMID 40647133, 2025). "This preliminary finding, which should be interpreted with caution and validated in a larger study, is in line with the emerging evidence that the JAK2 V617F mutation is a non-classical risk factor for cardiovascular disease." (PMID 39361963, 2024). "In addition to Tet2, mutations in DNA (cytosine-5)-methyltransferase 3A (DNMT3A), Additional Sex Combs-Like 1 (ASXL1) and Janus kinase 2 (JAK2) induce clonal hematopoiesis and cardiovascular disease." (PMID 32823583, 2020). "JAK2/STAT3 is a classic inflammatory pathway, exacerbating vascular dysfunction and contributing to the progression of cardiovascular diseases." (PMID 39257845, 2024).
blood cancer (16 papers, 2011 to 2025). "It is a rare and incurable blood cancer associated with the overproduction of blood cells in the bone marrow, part of a group of related blood cancers known as MPNs, with almost all patients having a mutation in the JAK2 gene." (PMID 38975402, 2024). "Our study presented one such case (patient #20) whose AITL developed after 10 years of PV and the two hematologic neoplasms shared three identical JAK2 and TET2 mutations." (PMID 34581268, 2021). "Mutations of the JAK2 gene and aberrations of chromosome band 9p24, where JAK2 maps, lead to rearrangements of JAK2 and have been reported in various hematologic neoplasms." (PMID 29262599, 2017). "Some of these biases were expected (e.g., KRAS in gastrointestinal cancers or JAK2 in blood cancers)." (PMID 41465353, 2025). "JAK kinases are established Hsp90 client proteins and here we show that the novel small molecule Hsp90 inhibitor ganetespib (formerly STA-9090) exhibits potent in vitro and in vivo activity in a range of solid and hematological tumor cells that are dependent on JAK2 activity for growth and survival." (PMID 21533169, 2011). "Ongoing structure–function studies of the EPOR and its essential partner, tyrosine kinase JAK2, suggest that it may be possible to generate new “designer” drugs that control selected subsets of cytokine receptor activities for therapeutic manipulation of hematopoiesis and treatment of blood cancers." (PMID 32983414, 2020). "To explore possible pathways downstream of JAK2 that could explain this link to myeloid diseases, we applied a machine learning approach (XGBoost) to AML TCGA data as a relevant and closely related blood cancer." (PMID 36192425, 2022).
hematopoietic neoplasms (14 papers, 2011 to 2025). "This haplotype spans several polymorphisms within the Jak2 gene and has been found to increase susceptibility to a variety of hematologic cancers." (PMID 41226376, 2025). "The JAK2 46/1 haplotype is a significant factor in both the development and therapeutic resistance of JAK2-associated hematologic cancers." (PMID 41226376, 2025). "It has been found to increase susceptibility to a variety of hematologic cancers, especially when linked with the somatic JAK2 V617F mutation, which results in the alteration of the JAK/STAT pathway, which is particularly essential for hematopoiesis." (PMID 41226376, 2025). "For this reason, the mutational landscape of JAK2 in the closed state is presented as a representative of JAK-driven hematopoietic neoplasms." (PMID 37834019, 2023). "Janus kinase 2 (JAK2) is a pivotal kinase in hematopoietic stem and progenitor cells (HSPCs), and its uncontrolled hyperactivation is a prominent oncogenic driver of hematopoietic neoplasms." (PMID 37317974, 2023). "In the BioVU cohort, 17 individuals with JAK2 V617F and 9p CN-LOH developed hematological cancers." (PMID 38225345, 2024).
inflammation (11 papers, 2019 to 2026). Aberrant reaction of the microcirculation characterized by movement of fluid and leukocytes from the blood into extravascular tissues. "After acute or chronic systemic inflammation, the JAK2/STAT3 pathway is closely associated with regeneration of the heart, lung, liver, and kidney tissues in lipopolysaccharide (LPS)-induced mice." (PMID 37650558, 2023). "Phospho-JAK2/STAT3 level were downregulated in FNDC5 OE mice, suggesting that the protective role of FNDC5 in cardiac inflammation are associated with JAK2/STAT3 pathway inhibition." (PMID 30940158, 2019). "Further molecular analysis revealed that both pulmonary inflammation and PF were associated with increased transforming growth factor-β1 (TGF-β1), Janus activated kinase 2 (JAK2), and signal transducer and activator 3(STAT3) expression in the lung tissues of model rats." (PMID 35120332, 2022). "β-carotene in White Lablab modulates macrophage polarization and activates the JAK2/STAT3 and JNK/p38 MAPK signaling pathways to attenuate lipopolysaccharide-induced intestinal inflammation in rats." (PMID 36188567, 2022).
kidney (9 papers, 2009 to 2025). "Here, we present an illustrative case of late in-stent thrombosis following carotid artery stenting (CAS) in a patient with ET and the JAK2 V617F mutation presenting with symptomatic internal carotid artery (ICA) stenosis." (PMID 38021556, 2023). "In the present study we have estimated the effect of JAK2 inhibitor tyrphostin AG-490 on zymosan-induced inflammation with focus on kidney dysfunction." (PMID 19416544, 2009).
metabolic disease (8 papers, 2018 to 2026). A congenital disorder (due to inherited enzyme abnormality) or acquired (due to failure of a metabolically important organ) disorder resulting from an abnormal metabolic process. "The overall findings provide experimental evidence of using Jak2 blockade therapy, which can modulate central and peripheral inflammatory responses and metabolic disorder after acute ischemic stroke." (PMID 34943061, 2021). "This clinical piece of evidence is consistent with our findings and it would indicate that because of ongoing Jak2 inhibition, leptin cannot exert its retroactive control on FI and BW, which would therefore favor BW gain and metabolic diseases over time." (PMID 29867515, 2018). "In conclusion, EAE may exert anti-PF effects associated with the structure of the gut microbiota, correction of amino acid metabolic disorders (notably tryptophan metabolism) and modulating JAK2/STAT3 signaling pathway in the lung." (PMID 42088464, 2026). "Thus, the JAK2/STAT3 signaling pathway seems to be one of the critical pathways regulating VSMC proliferation and resulting in the development of metabolic diseases." (PMID 35082965, 2022).
neurodegenerative disease (7 papers, 2020 to 2023). A disorder of the central nervous system characterized by gradual and progressive loss of neural tissue and neurologic function. "Age-related degeneration in the JAK2/STAT3 axis exerts crucial effect on the pathogenesis of neurodegenerative diseases." (PMID 33833662, 2021). "In our study, AG490 (a JAK2-specific inhibitor) was employed, aiming to figure out whether JAK2 involves in inflammation responses in leptomeningeal cells induced by cytokines from macrophages and whether it is a therapeutic target of neurodegenerative diseases." (PMID 33015166, 2020). "JAK2 and STAT3 are key members of the JAK/STAT pathway and play an important role in the pathophysiology of neurodegenerative diseases." (PMID 36627822, 2023). "The JAK2/STAT3 pathway plays a protective role for neuroinflammatory and neurodegenerative diseases such as SAD." (PMID 32655767, 2020). "Recent literatures reported that resveratrol could inhibit oxidation and apoptosis in neurodegenerative diseases through the Nrf2/HO-1, SIRT1, RAX/P-PKR, and JAK2/STAT3/PI3K/AKT/mTOR signaling pathways." (PMID 36836502, 2023). "JAK2/STAT3 activation, in particular, was illustrated to protect the neuron, while alteration of the same pathway might play a role in developing neurodegenerative diseases." (PMID 31996736, 2020). "Thus, targeting the JAK2/STAT3 pathway can be used as a protective therapy for neuroinflammatory and neurodegenerative diseases like AD." (PMID 32655767, 2020). "Thus, the JAK2/STAT3 signaling pathway was targeted to evaluate its crucial role in immune and inflammatory responses, as its dysregulation is a key factor in various neurodegenerative diseases." (PMID 36648973, 2023).
adenocarcinoma (6 papers, 2017 to 2024). A common cancer characterized by the presence of malignant glandular cells. "For instance, the expression of MMP 10 is regulated through the JAK2/STAT3 signaling in adenocarcinomas." (PMID 30220965, 2018). "Our data has also shown that leptin/LEPR signaling enhanced proliferation in the HEY3 and SKOV3 adenocarcinoma cell lines also via JAK2/STAT3." (PMID 29212170, 2017). "For instance, IL-6 regulates MMP 10 through JAK2/STAT3 signaling in adenocarcinomas." (PMID 30220965, 2018). "First, we examined the expression of NF-κB components, AICDA, Akt, JAK2/STAT3, and IL6 in PC9 (adenocarcinoma with the EGFR exon 19 deletion) and PC9/GR (adenocarcinoma with the EGFR-TKI-resistant with T790M mutation) cells, using Western blotting and RT-PCR." (PMID 35740609, 2022). "They observed that the expression levels of Bcl-2 and bcl-xl in the adenocarcinoma cell line increased with CXCL12 therapy and decreased with CXCR4 antagonist and JAK2 inhibitor therapy." (PMID 31718601, 2019).
kidney disease (6 papers, 2013 to 2025). "The JAK/STAT system mediates abnormal kidney diseases, and suppression of JAK2 expression can relieve DN progression." (PMID 30186548, 2018). "The Jak2/Stat signaling cascade is present in tubular epithelial and tubulointerstitial cells and is activated in various renal disease models." (PMID 28859164, 2017). "To highlight the value of UM30-OSN in modeling APOL1-mediated kidney disease with an APOL1 (G1/G0) genotype, we examined how Interferon-γ (IFN-γ) affects UM30-OSN–derived podocytes and assessed whether the JAK1/JAK2 inhibitor Baricitinib can counteract IFN-γ–induced cellular responses." (PMID 41225540, 2025).
neurological disorders (5 papers, 2020 to 2025). "The involvement of the JAK2/STAT3/Fyn/NMDA signaling pathway in these effects highlights DBZ as a potential candidate for treating neurological disorders associated with neuroinflammation." (PMID 40349773, 2025). "JAK1 and JAK2 have been extensively studied and seem to play the most predominant role, as mice knocked out (KO) for JAK1 exhibit severe lymphocyte damage and neurological disease, and JAK2 KO mice die in utero due to impaired hematopoietic functions." (PMID 41463071, 2025). "Allowing for the intricate role of JAK2 in diseases of the nervous system, identifying the exact effect of JAK2 on leptomeninges in PD is of vital importance." (PMID 33015166, 2020).
bacterial infection (3 papers, 2015 to 2024). "The fact that both JAK1 and JAK2 are imperative in the signaling cascade required for MHC II cell surface expression is well established, and their abrogation leading to decreased MHC II has been seen in certain bacterial infections." (PMID 25690042, 2015).
head and neck tumor (2 papers, 2015 to 2022). "Except for JAK2 and NKX2-1, all genes were differentially expressed in primary head and neck tumors as compared to normal tissue." (PMID 35954343, 2022).
overlap syndromes (2 papers, 2024 to 2025). "Although CBL’s role in MPN progression has been well-documented, emerging observations in overlap syndromes indicate that certain variants might unexpectedly limit proliferative signals through JAK2 destabilization." (PMID 40772034, 2025).
brain disorder (1 paper, 2022). A disease affecting the brain or part of the brain. "Clinical studies have also shown that dysregulation of the expression of JAK1 and JAK2 associates with brain inflammatory processes and neuronal or glial survival, which are consequently involved in most brain disorders including the pathogenesis of AD." (PMID 35701806, 2022).
central nervous system diseases (1 paper, 2025). "Furthermore, studies have shown that inhibiting the excessive activation of JAK2/STAT3 is an effective neuroprotective strategy in central nervous system diseases." (PMID 41208867, 2025).
vasculopathy (1 paper, 2025). "We demonstrate in a mouse model of CAV that blockade of JAK1 and JAK2 signaling with Ruxolitinib reduces vasculopathy and prolongs allograft survival." (PMID 41333445, 2025).
JAK2 also shares sentences with these, for which no sentence is quoted: psoriatic arthritis (10 papers); chronic neutrophilic leukemia (7); Cirrhosis (7); dermatitis (7); squamous cell carcinoma (7); acute myocardial infarction (5); pneumonia (5); T-cell acute lymphoblastic leukemia (5); venous thromboembolism (5); acute respiratory distress syndrome (4); B-cell precursor acute lymphoblastic leukemia (4); coagulation defects (4); multiple sclerosis (4); refractory anemia (4); renal failure (4); vasculitis (4); alopecia (3); Behcet disease (3); hypersplenism (3); juvenile idiopathic arthritis (3); juvenile myelomonocytic leukemia (3); lymphoid leukemia (3); retinoblastoma (3); acute aortic dissection (2); acute promyelocytic leukemia (2); alcoholic hepatitis (2); antithrombin deficiency (2); beta thalassemia (2); bone marrow disease (2); cerebrovascular disease (2).
A further 203 diseases each share a sentence with JAK2 in 2 papers or fewer.